AGO2 (argonaute RISC catalytic component 2)
Diseases named in the same sentence as AGO2 in open-access papers (continued):
Sharing a sentence is not in itself a finding about the gene and the disease.
heart failure (6 papers, 2017 to 2025). Inability of the heart to pump blood at an adequate rate to meet tissue metabolic requirements. "We observed that nuclear and mitochondrial Ago2 have been increasingly implicated in the pathogenesis of various cardiovascular diseases, such as hypertension, diabetic cardiomyopathy, and heart failure." (PMID 40861070, 2025). "Recently, we confirmed that Ago2 is intricately involved in the pathological processes of heart failure, particularly through its role in cardiac remodeling and functional impairment." (PMID 40861070, 2025). "In a mouse model of heart failure induced by transverse aortic constriction, an increase in Ago2 levels was observed in both the cytoplasm and nuclei of cardiomyocytes, resulting in a detrimental impact on cardiac function." (PMID 40861070, 2025). "In our unpublished research (Patent Number: ZL20221 1079886.4), rAAV9-mitochondrial Ago2 also protected against transverse aortic constriction (TAC) pressure overload induced heart failure." (PMID 40861070, 2025). "Previous studies on AGO2 had proved its important roles in the developmental processes including neural tube closure, cardiac failure, and even embryonic lethal." (PMID 28903378, 2017). "Moreover, RNA-pulldown experiments and AGO2-immunoprecipitation experiments revealed that hsa_circ_0097435 potentially served a role in heart failure by sponging multiple microRNAs." (PMID 32211036, 2020). "With the aid of Ago2 CLIP-seq data, luciferase assays verified that RBFox2 was targeted by multiple miRNAs, including Let-7, miR-16, and miR-200b, which were significantly upregulated in heart failure." (PMID 36674797, 2023).
liver cancer (6 papers, 2017 to 2023). An epithelial or non-epithelial malignant neoplasm that arises from the liver. "Among the genes associated with the prognosis of liver cancer, the genes associated with shorter survival period are AGO2, DCPS, IFIT5, LARP1, NCBP2, NUDT10, and NUDT16; the genes associated with longevity are EIF4E3, EIF4G3, METTL1, NCBP1, NSUN2, NUDT11, NUDT4, and WDR4." (PMID 36845384, 2023). "In comparison, relatively high correlation between AGO2 protein and mRNA levels was observed in two liver cancer cell lines." (PMID 32420319, 2020). "Further experimental analyses demonstrated that the up-regulation of FAK expression in liver cancer is mediated by Argonaute2 (Ago2), a protein involved in miRNA maturation." (PMID 28067792, 2017). "Therefore, in this study, anti-Ago2 antibodies were used in RNA immunoprecipitation (RIP) experiments in liver cancer cisplatin-resistant cell extracts to determine whether FER1L4 and miR-106-5p/miR-372-5p belong to the same RISC." (PMID 33868788, 2021). "As miRNAs are part of ribonucleoprotein complexes (RNPs), which additionally contain RNA-binding proteins like Argonaute 2 (AGO2), we performed an AGO2-RNA immunoprecipitation (IP) using HepG2 and HuH7 liver cancer cells, which showed high LINC00152 expression levels." (PMID 35563834, 2022).
osteosarcoma (6 papers, 2021 to 2024). A usually aggressive malignant bone-forming mesenchymal neoplasm, predominantly affecting adolescents and young adults. "Moreover, the importance of AGO2 in the DDR pathway is manifested by the impairment of the DNA repair potential of AGO2-deficient osteosarcoma cells." (PMID 33668654, 2021). "Further experiments revealed that nuclear miR‐1246 accelerated MNNG cell migration through upregulating migration genes via targeting its enhancers dependent on the AGO2 protein, highlighting the therapeutic potential of miR‐1246 for osteosarcoma." (PMID 38585233, 2024). "This study highlights that EVs‐derived miR‐1246 promotes osteosarcoma cell migration through activating MMP1 via NamiRNA‐enhancer network dependent on AGO2." (PMID 38585233, 2024). "Subsequent RIP assay results demonstrated that circ0038632, DNMT3A, and miR-186 enrichment was majorly raised in anti-AGO2 group in osteosarcoma cells." (PMID 36059626, 2022). "The results showed that circVRK1 and miR-337-3p were dramatically enriched in the AGO2-antibody precipitated RNA fraction in osteosarcoma cells." (PMID 34424826, 2021). "Thus, we chose EVs‐derived miR‐1246 as an example of the potent NamiRNAs to clarify how NamiRNAs modulate osteosarcoma metastasis and explore the roles of AGO2 during this process." (PMID 38585233, 2024). "However, it remains uncertain whether EVs‐derived miRNAs participate in osteosarcoma metastasis as NamiRNAs and how AGO2 regulates NamiRNA‐targeted transcriptional activation in this procedure." (PMID 38585233, 2024). "Besides, it has been demonstrated that silencing AGO2 could significantly inhibit osteosarcoma cell migration, further supporting that AGO2 regulates osteosarcoma metastasis caused by miR‐1246 mediated gene activation." (PMID 38585233, 2024). "Besides, AGO2 knockdown could significantly inhibit the migratory ability of osteosarcoma cells, indicating that AGO2 may regulate osteosarcoma metastasis." (PMID 38585233, 2024).
pancreatic cancer (6 papers, 2019 to 2024). "Here, in a mouse model of mutant KRAS-driven pancreatic cancer, loss of AGO2 allows precursor lesion (PanIN) formation yet prevents progression to pancreatic ductal adenocarcinoma (PDAC)." (PMID 32499547, 2020). "Here, a GEMM of AGO2 loss delineates pancreatic cancer development into two distinct phases." (PMID 32499547, 2020). "It has been shown that both KRAS and EGFR are essential mediators of pancreatic cancer development and they were shown to interact with Argonaute 2 (AGO2) to perturb its function." (PMID 37686149, 2023). "Both KRAS and EGFR are essential mediators of pancreatic cancer development and interact with Argonaute 2 (AGO2) to perturb its function." (PMID 32499547, 2020). "Here, we employed established mouse models of pancreatic cancer to determine the in vivo requirement of AGO2 in pancreatic cancer development." (PMID 32499547, 2020). "To investigate the role of AGO2 in the development of pancreatic cancer in vivo, we employed the GEMM of pancreatic cancer initiated by a conditionally activated allele of KRAS4, KRASLSL−G12D/+ (KRASG12D)." (PMID 32499547, 2020). "Transcript analysis in human pancreatic cancer suggested a significant increase in AGO2 expression in PDAC compared with normal pancreas." (PMID 32499547, 2020). "Notably, other members of the Argonaute family fail to compensate for these functions, reiterating the specific role of AGO2 in KRAS-driven pancreatic cancer." (PMID 32499547, 2020). "In support of this hypothesis, both LINC00346 and miR-188-3p were detected in Ago2 immunoprecipitates from pancreatic cancer cells." (PMID 30728036, 2019). "Together, these data indicate that during pancreatic cancer development, AGO2 localizes at the plasma membrane, the site of RAS activity, and substantiates a role for AGO2 in the progression of PanINs to PDAC." (PMID 32499547, 2020). "Altogether, our study supports a biphasic model of pancreatic cancer development: an AGO2-independent early phase of PanIN formation reliant on EGFR-RAS signaling, and an AGO2-dependent phase wherein the mutant KRAS-AGO2 interaction is critical for PDAC progression." (PMID 32499547, 2020). "Here, the authors establish a KRAS-driven mouse model of pancreatic cancer with conditional loss of AGO2 and show that the early phase of neoplastic lesion initiation is dependent on EGFR/RAS but not AGO2, while AGO2 is required for pancreatic ductal adenocarcinoma progression and metastasis." (PMID 32499547, 2020).
pancreatic ductal adenocarcinoma (6 papers, 2019 to 2022). An infiltrating adenocarcinoma that arises from the epithelial cells of the pancreas. "Moreover, AGO2-mutated KRAS interaction holds crucial importance in pancreatic ductal adenocarcinoma progression, where AGO2 expression is required for overcoming oncogene-induced senescence and cancer development." (PMID 33668654, 2021). "AGO2 protein–protein interactions (e.g., KRAS and AGO2) are involved in the progression of pancreatic ductal adenocarcinoma and NSCLC." (PMID 36012592, 2022).
cardiac hypertrophy (5 papers, 2021 to 2025). "Another interesting new finding was that m6A modification enhanced the recruitment of miR-133a-RISC (RNA-induced silencing complexes)-AGO2 (Argonaute 2-Insulin-like growth factor 2) to its targets in heart development and in response to cardiac hypertrophy and proliferation." (PMID 35858921, 2022). "Several studies have demonstrated the involvement of circRNAs in the pathogenesis of myocardial hypertrophy, via sponging miRNAs 23-25; however, an RNA pull-down assay in this study revealed that CHACR did not bind to AGO-2, as an indicator protein for circRNAs to function as sponges." (PMID 40093901, 2025).
COVID-19 (5 papers, 2021 to 2025). A disease caused by infection with severe acute respiratory syndrome coronavirus 2. "It was determined that expression level of Ago2, Dicer, and Drosha were significantly downregulated (Log FC: − 3.46, − 1.92, − 4.23, respectively) in COVID-19 patients compared with control group." (PMID 34715923, 2021). "Our findings demonstrated that the expression of Dicer, Drosha, and Ago2 was statistically altered in COVID-19 patients compared to healthy subjects." (PMID 34715923, 2021). "We found that the expression levels of Dicer, Drosha, and Ago2 were significantly reduced in patients with COVID-19 compared with healthy individuals." (PMID 34715923, 2021). "In conclusion, we observed the dysregulation of key RNAi components, Dicer, Ago2, and Drosha, as crucial antiviral defense factors in RNAi system in COVID-19 patients." (PMID 34715923, 2021). "Notably, diminished levels of AGO2 mRNA are reported in COVID-19 patients in comparison to healthy individuals." (PMID 40219968, 2025). "Dicer, Drosha, Ago2, and DGCR8 (critical components of RNAi) were selected for evaluation in COVID-19 patients." (PMID 34715923, 2021). "Dicer, Drosha, Ago2, and DGCR8 are essential components of the RNAi system, which is supposed to be dysregulated in COVID-19 patients." (PMID 34715923, 2021). "mRNA levels of AGO2, DICER1, DGCR8, DROSHA, and Exportin-5 (XPO5) were measured by quantitative reverse-transcription polymerase chain reaction (RT-qPCR) in nasopharyngeal swab specimens from patients with COVID-19 and controls, as well as in cells infected with SARS-CoV-2 in vitro." (PMID 37243263, 2023). "Measured mRNA levels of AGO2, DICER1, DGCR8, DROSHA, and XPO5 were not significantly different in nasopharyngeal swab specimens of severe COVID-19 patients compared to non-severe COVID-19 patients or controls." (PMID 37243263, 2023). "Our data showed that the mRNA expression levels of AGO2, DICER1, DGCR8, DROSHA, and XPO5 were not significantly different in patients with severe COVID-19 when compared to patients with non-severe COVID-19 and controls." (PMID 37243263, 2023).
non-small cell lung carcinoma (5 papers, 2021 to 2026). A group of at least three distinct histological types of lung cancer, including non-small cell squamous cell carcinoma, adenocarcinoma, and large cell carcinoma. "In Non-Small Cell Lung Carcinoma (NSCLC) patients, high levels of AGO2 phosphorylation at S417 (pS417-AGO2), which is surface exposed but not positioned in close proximity of the RNA-binding channel, correlates with a decreased prognosis." (PMID 40863728, 2025).
Sepsis (5 papers, 2020 to 2025). Sepsis is defined as life-threatening organ dysfunction caused by a dysregulated host response to infection. "As miR-93-5p expression was upregulated in baboons upon sepsis induction, we next examined how many of the AGO2 IP–identified 583 putative miR-93-5p targets also showed lowered expression levels in the sepsis baboon models by genome-wide gene expression." (PMID 37261908, 2023). "They showed that miR-21a-3p levels in plasma and TECs increased during sepsis by the internalization of plasmatic Ago2, which binds miR-21a-3p mediated by membrane Nrp-1." (PMID 36012630, 2022). "Firstly, miR-21a-3p and Ago2 levels were found out to increase in both plasma and TECs during sepsis, and the increase of intracellular Ago2 and miR-21a-3p could be mitigated when Ago2 was either inactivated or downregulated in septic plasma." (PMID 32923478, 2020). "Moreover, membrane Nrp-1 expression of TECs was increased significantly during sepsis and Nrp-1 knockdown also mitigated the rise of both the intracellular Ago2 and miR-21a-3p levels in TECs incubated with septic plasma." (PMID 32923478, 2020). "We performed feature selection analysis and found that combination of three genes (TLCD4, PRSS30P, and ZNF493) and seven genes (TLCD4, PRSS30P, ZNF493, AGO2, SLC37A3, SLC2A1, and RPL11) showed moderate performance in identifying patients with sepsis and ARDS within 1 day after admission." (PMID 33818300, 2021).
Alzheimer disease (4 papers, 2017 to 2022). A progressive, neurodegenerative disease characterized by loss of function and death of nerve cells in several areas of the brain leading to loss of cognitive function such as memory and language. "Supermeres are highly enriched with cargo involved in multiple cancers (glycolytic enzymes, TGFBI, miR-1246, MET, GPC1 and AGO2), Alzheimer’s disease (APP) and cardiovascular disease (ACE2, ACE and PCSK9)." (PMID 34887515, 2021).
cocaine addiction (4 papers, 2014 to 2023). "Upregulation of the Ago2, protein that partakes miRNA production and execution of miRNA-mediated gene silencing was implicated in the regulation of cocaine addiction and anorexia." (PMID 29179434, 2017). "Moreover, they observed that Ago2 had a role in cocaine addiction due to ago2-dependent miRNAs and, specifically miRNAs with a potential role in neural plasticity and motivation to consume cocaine." (PMID 38069445, 2023). "Interestingly, AGO2 in dopamine 2 receptor-expressing neurons regulates cocaine addiction, and nuclear AGO2 has been reported to regulate voltage-gated potassium channels in adipose tissue-derived stromal cells with crucial functions in the self-renewal and cell de-aging processes." (PMID 24904827, 2014). "Nevertheless, the observed role of Ago2 in cocaine addiction and METH sensitization indicated that Ago2 may play an important role in regulating drug addiction with a neural type-specific pattern." (PMID 34483916, 2021).
Insulin resistance (4 papers, 2014 to 2022). Increased resistance towards insulin, that is, diminished effectiveness of insulin in reducing blood glucose levels. "To address whether Ago2 mediates the compensatory expansion of β cells during insulin resistance, we next crossed mice carrying the Ago2-floxed allele onto the ob/ob background to generate mice deficient in both Ago2 and leptin (Ago2ob)." (PMID 24361012, 2014). "Here, we show that the onset of insulin resistance induces the silencing of miR-184 in order to promote the function of Ago2 in the pancreatic β cell." (PMID 24361012, 2014). "Here, we show that miR-184 is silenced during insulin resistance to promote the expression of Ago2 in the pancreatic β cell." (PMID 24361012, 2014). "Two gain-of-function models for miR-184 were then generated in order to restore its expression in the β cell and validate the regulation of Ago2 by this miRNA during insulin resistance." (PMID 24361012, 2014).
myeloid leukemia (4 papers, 2013 to 2023). A clonal proliferation of myeloid cells and their precursors in the bone marrow, peripheral blood, and spleen. "This was especially pronounced in the myeloid leukemia cell line KASUMI-1 with 46 (48%) of all Ago-associated miRNAs specifically bound to Ago2, while 37% of miRNAs were associated with all four Argonaute proteins." (PMID 23418555, 2013). "Targeting oncogenic miRNAs by knock down of argonaute 2 (AGO2) has shown to induce apoptosis in myeloid leukemia." (PMID 36009578, 2022).
autoimmune disease (3 papers, 2016 to 2024). A disorder resulting from loss of function or tissue destruction of an organ or multiple organs, arising from humoral or cellular immune responses of the individual to their own tissue constituents. "While AGO2 has been described as the targeted antigen in autoimmune disease (AID)-related studies, we found both AGO1 and AGO2 to be targeted." (PMID 36341350, 2022). "AGO1- and AGO2-Abs mediate more serious autoimmune diseases." (PMID 38887290, 2024).
cholangiocarcinoma (3 papers, 2020 to 2024). A carcinoma that arises from the intrahepatic biliary tree (intrahepatic cholangiocarcinoma) or from the junction, or adjacent to the junction, of the right and left hepatic ducts (hilar cholangiocarcinoma). "RIP assay showed the abundant enrichment of HCG18 and miR-424-5p in the precipitates of anti-Ago2, which indicated that HCG18 bound with miR-424-5p in cholangiocarcinoma cells." (PMID 36854894, 2023).
Cirrhosis (3 papers, 2023 to 2025). A chronic disorder of the liver in which liver tissue becomes scarred and is partially replaced by regenerative nodules and fibrotic tissue resulting in loss of liver function. "AGO2-Abs notably increased in cirrhosis, decompensation, and further in ACLF, unlike AGO1-Abs and AGO3-Abs." (PMID 39119295, 2024).
epilepsy (3 papers, 2023 to 2025). A brain disorder characterized by episodes of abnormally increased neuronal discharge resulting in transient episodes of sensory or motor neurological dysfunction, or psychic dysfunction. "Here, we analyzed Ago2‐immunoprecipitated small RNA‐Seq data along with matching transcriptomic and proteomic data across seven defined timepoints in a rat model of epilepsy that was induced using perforant pathway stimulation (PPS)." (PMID 41392969, 2025). "This indicates that changes to the integrity of the blood brain barrier in epilepsy are likely sufficient to allow direct passage of a protein the size of Ago2 into the blood." (PMID 37808470, 2023). "To explore the link between circulating miRNAs and the pathophysiology of epilepsy, we first sequenced argonaute 2 (Ago2)-bound miRNAs in plasma samples collected from mice subject to status epilepticus induced by intraamygdala microinjection of kainic acid." (PMID 37808470, 2023). "Several of the same human epilepsy circulating miRNAs were detected here, bound to Ago2 in the plasma of mice." (PMID 37808470, 2023). "To determine if some of the circulating miRNA biomarkers of epilepsy originate from the brain, and to establish whether any of these are from neurons, we generated mice that express a FLAG-tagged Ago2 protein under a neuron- or microglial-specific promoter." (PMID 37808470, 2023).
head and neck squamous cell carcinoma (3 papers, 2017 to 2022). A squamous cell carcinoma that arises from any of the following anatomic sites: lip and oral cavity, nasal cavity, paranasal sinuses, pharynx, larynx, and salivary glands. "On the contrary, FAK acts as a key mediator in cell-ECM interactions that contributed to tumorigenesis and progression by stimulating AGO2 to activate the FAK/PI3K/Akt signaling pathway in head and neck squamous cell carcinomas." (PMID 36613808, 2022). "Argonaute 2 (AGO2) protein is usually overexpressed in various head and neck squamous cell carcinoma." (PMID 28903378, 2017). "To explore the relationship between p63 and Ago2, we studied tumor cell lines derived from head and neck squamous cell carcinoma (HNSCC) and NSCLC." (PMID 35459267, 2022). "In this study, we demonstrated that the expression of AGO2 was up-regulated in hypopharyngeal cancer at both mRNA and protein levels compared with adjacent noncancerous epithelium, which was in according with similar study in head and neck squamous cell carcinoma." (PMID 28903378, 2017).